FTO (FTO alpha-ketoglutarate dependent dioxygenase)
Diseases named in the same sentence as FTO in open-access papers (continued):
Sharing a sentence is not in itself a finding about the gene and the disease.
Obesity (continued). "As rs9939609 has been the representative variant of FTO, a direct effect of FTO conferred to PCOS has been revealed regardless of obesity or BMI." (PMID 23840863, 2013). "The effect of KLF14 is reportedly not driven by obesity, quite unlike the known BMI- and fat mass mediated effect of FTO via insulin resistance." (PMID 24098730, 2013). "The rare missense mutations of FTO and SH2B1 do not confer risks of obesity in Chinese Han children in our cohort." (PMID 23825611, 2013). "Taken together we found evidence that rs9939609 in the FTO and rs6536991 in the UCP-1 gene increased the risk of obesity but not obesity related phenotypes in the Brazilian population studied." (PMID 23134754, 2012). "The association of both FTO and UCP-1 polymorphisms with the obesity phenotype in the Brazilian population has not been reported, and that was the aim of the present study." (PMID 23134754, 2012). "We show that expression of the “obesity gene” FTO is not significantly affected by adipocyte differentiation or metabolic regulators related to glucose and insulin metabolism in our cell models of human subcutaneous adipocytes." (PMID 21687707, 2011). "However, not all individuals possessing FTO gene variants are overweight or obese, suggesting that possible interactions with other genetic and/or environmental factors could be necessary for promoting weight gain and obesity." (PMID 22043166, 2011). "In PCOS, FTO variation seems to be a key marker for IR, either directly i.e. to some degree independent of BMI/obesity or secondary due to its impact on body weight which in turn has an impact on glucose intolerance and diabetes." (PMID 20092643, 2010). "As both FTO and MC4R are known to affect type 2 diabetes risk through modulation of obesity, association was also calculated without adjustment for BMI." (PMID 20161779, 2010). "However, since the obesity-associated SNPs do not affect the coding region of FTO, whether the connection to obesity works through the function of FTO per se is still a question, since the SNPs may exert influence on the expression of distant genes other than FTO." (PMID 21103374, 2010). "Similarly, testing for categorical BMI showed that FTO was not a significant predictor for obesity in either of the adjusted genetic models: the dominant model (p = 0.66) or the additive model (p = 0.39)." (PMID 39925495, 2025). "Interestingly, FTO expression exhibited a sex-dependent pattern: boys without obesity showed the highest expression levels, followed by boys with obesity, while girls with obesity had the lowest expression levels." (PMID 40806129, 2025). "On the other hand, these approaches accentuated the role of the MMP2 gene at the FTO locus in skeletal myotubes, given its consistency within the GnRH signaling pathway, which is in line with previous studies linking its expression with obesity." (PMID 39813287, 2025). "FTO belongs to the AlkB family of non-heme iron(ii)-dependent and α-ketoglutarate-dependent dioxygenases, which are known to modulate various biological processes, including body mass and obesity development." (PMID 40356725, 2025). "However, this research has the advantage of being conducted in a Mexican population, where other studies have analyzed FTO SNPs, but with a focus on obesity and T2DM rather than cancer." (PMID 39040764, 2024). "Moreover, research on inhibitors targeting FTO and ALKBH5 is advancing, with diverse inhibitors identified through high-throughput screening and structural optimization, demonstrating significance in targeting tumors, obesity, and other diseases." (PMID 39192357, 2024). "Notably, individuals with the CLOCK (CC), FTO (AA), and LEP (AA) genotypes exhibited the highest BMI and WHR, while those with GHRL (TT), MC4R (CC), and LEPR (GG) genotypes, although showing lower values, were still correlated with overweight and obesity." (PMID 39203789, 2024).
Obesity (continued). "These associations may reflect genetic contributions to baseline weight rather than weight change, as FTO is among the strongest known loci for obesity, and follow-up metrics are strongly positively correlated with baseline obesity." (PMID 38987242, 2024). "Individuals carrying 30685GG and -23525AA genotypes have twice more risk for developing obesity than non-carriers suggesting that FTO 30685GG and -23525AA might be a good predictor for obesity in this population." (PMID 39253342, 2024). "This suggests that the FTO gene may influence the development of endometrial cancer through biological pathways that are independent of obesity." (PMID 39175477, 2024). "These obesity-associated SNPs may increase body weight by altering the expression of other genes, such as IRX3 and RPGRIP1L, rather than the FTO gene." (PMID 37752455, 2023). "However, because FTO was only recently established as an m6A eraser, the contexts in which FTO promotes obesity in an m6A-independent or dependent manner is not entirely clear." (PMID 35350378, 2022). "Additionally, the FTO SNP rs8050136 in humans decreases the binding affinity of the CUX1 isoform P110, resulting in decreased expression of FTO and leptin signaling, preventing satiety, and promoting obesity." (PMID 35350378, 2022). "FTO and ALKBH5 primarily demethylate m6A- modified bases, with FTO being the first m6A demethylase identified, showing high demethylation activity for m6A, and ALKBH5 catalyzing the removal of m6A modifications from nuclear RNAs (mainly mRNA), thereby affecting metabolic disease and human obesity." (PMID 36118041, 2022). "This extract significantly down-regulates FTO via its highest binding affinity, but up-regulates the signal transducer and activator of transcription 3 (STAT-3) and reduces insulin resistance in high-fat diet-induced obesity in rats, possibly contributing to its use in the management of obesity." (PMID 34684698, 2021). "The link of FTO expression to fasting and obesity is not yet fully elucidated in humans, where more factors may interplay to determine this effect." (PMID 35372458, 2021). "The role of FTO protein in obesity is not completely elucidated." (PMID 32154826, 2020). "Moreover, obesity-associated SNPs correlated with IRX3 expression in the human brain, but not with that of FTO—suggesting that the association signal overlaps an enhancer element involved in long-range regulation of IRX3 in the brain." (PMID 32603637, 2020). "Some results have suggested that SNPs in FTO gene might not influence obesity and diseases of affluence directly, but rather epigenetically impact the expression of neighboring genes: IRX3 or RPGIP1L19–21." (PMID 32747736, 2020). "Having noted that obesity or diabetes status of the participants does not have an effect on the association signal between SLM, TBW, weight, and the genotypes of TC+CC at the FTO variant, we analyzed the remaining traits and biomarkers of the 60 that we began with using the linear regression model." (PMID 32076432, 2019). "The top obesity-associated locus illustrates well this model, in which the risk variant resides in an intronic enhancer at FTO and regulates the expression of two distal genes (IRX3 and IRX5), but not the FTO gene [54, 55•]." (PMID 31754873, 2019). "However, the molecular mechanisms responsible for the effect of FTO gene on obesity are not known yet." (PMID 31007685, 2019). "In the human brain, obesity-associated FTO SNPs correlated with higher expression of IRX3, but not FTO, indicating that increased expression of IRX3 may be due to the genetic variation within FTO being responsible for the obesity-associated phenotypes." (PMID 31482095, 2019). "Variants in this gene have previously been shown to associate with birthweight and the development of obesity and diabetes Their functional impact may be in modifying expression of the IRX3 and IRX5 genes, rather than FTO itself." (PMID 31616461, 2019).
Obesity (continued). "Some recent studies have suggested that the association between FTO SNPs in intron 1 and obesity might be owing to their potential influence on expression of IRX3, IRX5, and RPGRIP1L, rather than on their expression of FTO." (PMID 30105001, 2018). "A recent study indicates that the obesity association of the first intron does not imply FTO as the causal gene, but IRX3 located downstream on the same chromosome which is regulated by the first intron of FTO." (PMID 26828654, 2016). "Since most GWAS can only detect a locus but not a gene the question arose whether FTO is “the sole” obesity gene." (PMID 26431034, 2015). "Smemo and colleagues report that the region encompassing the SNPs form long-range connections with the promoter of the downstream IRX3, and that the obesity-associated SNPs in FTO intron 1 are associated with expression of IRX3, but not FTO, in samples of human cerebellum." (PMID 25242086, 2014). "In addition, three articles were excluded as they investigated the association between the FTO polymorphism and risk factors for CVD, e.g., obesity, hypertension, diabetes and insulin resistance." (PMID 23977173, 2013). "Several GWAS of body mass index (BMI) and/or obesity have been performed, and the first wave resulted in the suggestion of SNPs in/near the INSIG2, FTO, PFKP, and CTNNBL1 genes, however, only SNPs in the FTO locus were convincingly replicated in other GWAS and independent replication studies." (PMID 21912638, 2011). "The obesity genes MC4R, FTO and SH2B1 may participate in the central control of energy homeostasis." (PMID 19878575, 2009). "Several genes isolated through these studies, including FTO and MC4R, may eventually help scientists to explain the global scale of the obesity epidemic and the biological mechanism for the heritability of obesity in families." (PMID 19527601, 2009). "Besides FTO, genome wide association studies revealed that two non-synonymous variants in high linkage disequilibrium (H215R/I858V) in the Niemann-Pick C1 (NPC1) gene were associated with extreme obesity in European adults." (PMID 25825681, 2015). "Moreover, the lack of association of FTO with BMI in adults is consistent with its most significant association with class III obesity, and the fact that only 2% of the adults included in this cohort had this class of obesity." (PMID 23950976, 2013). "We postulate that risk alleles of SNPs in FTO (rs8050136, rs9939609) or causal variants genetically linked with them may specifically promote risk of IFH in Han Chinese, which is partially independent of general obesity (evaluated by BMI)." (PMID 23990951, 2013). "This study examined the relationship between appetite-regulating hormones and the expression of FTO and MC4R genes in the gastric tissue of patients with and without obesity." (PMID 41423640, 2025). "MEG3 and FTO showed sex-dependent expression in children without obesity, while additional sex-related differences were observed for SREBP1, FASN, ACACA, FTO, and MEG3 in children with obesity." (PMID 40806129, 2025). "It is thus apparent that FTO serves as a direct driving force of HCC, rather than an indirect influence akin to its effects on obesity and diabetes." (PMID 40316995, 2025). "Therefore, our findings were not surprising as FTO may interact with ApoA1 in regulating weight, TBW, and SLM and thus affects obesity and also corroborate studies showing SNPs from ApoA1 associated with lower levels of HDL as obesity risk factors." (PMID 32076432, 2019). "Results on FTO were compared with results on MCR4 (rs17782313), which is also an influential gene, albeit not with the same impact as FTO in relation to obesity." (PMID 28384342, 2017). "No other significant associations between any SNP and hypertension, hyperlipidemia and diabetes were noted after correction for BMI and no significant synergistic effect between FTO and UCP-1 SNPs with obesity were noted." (PMID 23134754, 2012).
Obesity (continued). "FTO and NAMPT/PBEF/visfatin are thought to play a role in obesity but their transcriptional regulation in adipocytes is not fully understood." (PMID 21687707, 2011). "However, similar to the FTO gene, not all individuals possessing MC4R gene variants are overweight or obese, again suggesting that possible interactions with other genetic and/or environmental factors could be necessary for promoting weight gain and obesity." (PMID 22043166, 2011). "However, the relationship between FTO and HCC does not stop there; research has demonstrated that obesity-induced hepatic steatosis, fibrosis, and HCC can be three separate processes." (PMID 40316995, 2025). "The absence of FTO can prevent high-fat diet-induced insulin resistance and hyperinsulinemia by enhancing AKT phosphorylation and also prevent obesity-induced hypertension by increasing the expression of prostaglandin D synthase, which preserves myogenic tone in resistance arteries." (PMID 40662138, 2025). "First, although we excluded the currently known FTO gene and performed reanalysis with adjustment for BMI, TC, LDL, and serum adiponectin, we could not completely rule out the effect of obesity on testosterone levels." (PMID 37900148, 2023). "Therefore, we hypothesize that the expression of FTO directly affects the biological behavior of HCC cells, rather than through indirect effects of obesity or fatty liver." (PMID 40316995, 2025).
type 2 diabetes (178 papers, 2007 to 2026). "In type 2 diabetes, a trial in patients (both men and women aged 40–70 y) found that 300 mg/d for 2 mo lowered BMI and blood pressure but only in carriers of the FTO-rs9939609 A allele." (PMID 41106481, 2025). "Association between FTO gene polymorphisms and type 2 diabetes has been verified in many races, supporting the clinical correlation between FTO and diabetes." (PMID 38297099, 2024). "Further emphasizing the role of dietary patterns, adherence to the Mediterranean dietary pattern, rich in fiber, has shown interactions with the FTO-rs9939609, linking a low adherence to the diet with higher type 2 diabetes risk in risk allele carriers." (PMID 38398881, 2024). "The FTO rs178117119 is implicated in the BMI-mediated risk of developing type 2 diabetes mellitus among obese children and adolescents." (PMID 38474283, 2024). "In one study that analyzed a CpG site in the first intron of FTO, the authors observed small but significant hypomethylation (P = 0.000021) upstream rs1121980 FTO polymorphism in patients with type 2 diabetes mellitus (T2DM) relative to controls." (PMID 39040764, 2024). "The current meta-analysis revealed that FTO rs8050136 significantly increases the risk of type 2 diabetes in the Asian population under all genetic models." (PMID 38033012, 2023). "For instance, it was demonstrated that carriers of the type 2 diabetes and obesity risk allele FTO-rs9939609 suffering from type 2 diabetes showed a better response to EGCG in terms of BMI improvement and diastolic blood pressure." (PMID 35743146, 2022). "The authors analyzed the correlations of single-nucleotide polymorphisms (SNPs) of the FTO gene, current BMI, BMImax and type 2 diabetes, and found that SNPs within FTO influence the development of type 2 diabetes by acting on BMImax." (PMID 35721732, 2022). "GCKR, a hub gene identified simultaneously by the susceptibility variants of alcohol consumption and type 2 diabetes, has densely interacted with type 2 diabetes-related genes such as FTO and SLC2A2." (PMID 34830198, 2021). "One study has identified FTO as one of the type 2 diabetes susceptibility genes regulating the adipogenesis." (PMID 33611339, 2021). "FTO was initially identified because of the strong association of multiple SNPs in its first intron with type 2 diabetes." (PMID 33461172, 2021). "The association of genetic variations in FTO with the risk of type 2 diabetes in multiple human populations and ethnic groups reveals that FTO plays an important role in glucose metabolism." (PMID 33162550, 2020). "In another, among 33 type 2 diabetes risk alleles, three (in FTO, TCF7L2 and PRC1) were found to be associated with breast cancer." (PMID 32705315, 2020). "In one study, among 37 type 2 diabetes risk alleles, two (in FTO and MTNR1B) showed nominally positive associations with pancreatic cancer risk and one showed an inverse association (in BCL11A)." (PMID 32705315, 2020). "In type 2 diabetics, elevated FTO protein expression has been associated with reduced glucose oxidation and blunted suppression of fat oxidation in insulin-stimulated conditions." (PMID 31635368, 2019). "We have identified FTO locus as a novel locus for conferring susceptibility to diabetic nephropathy in Japanese patients with type 2 diabetes." (PMID 30566433, 2018). "In 2007, a genome-wide association study (GWAS) searching for type 2 diabetes-susceptibility genes confirmed a common variant (rs9939609) in the FTO gene that predisposes European populations to diabetes." (PMID 28208657, 2017). "Given that the FTO locus has also been associated with Type 2 Diabetes, we reran the analysis excluding all Type 2 Diabetes cases (n = 2,540), The association for the FTO SNP rs55872725 remained strongly significant (β = 0.41, p = 4.25x10-18)." (PMID 28301549, 2017). "Good adherence to the Med Diet weakened the association of FTO rs9939609 polymorphism and type 2 diabetes." (PMID 28954439, 2017).